PANK4 (pantothenate kinase 4 (inactive))
Description:
Phosphatase which shows a preference for 4'-phosphopantetheine and its oxidatively damaged forms (sulfonate or S-sulfonate), providing strong indirect evidence that the phosphatase activity pre-empts damage in the coenzyme A (CoA) pathway. Hydrolyzing excess 4'-phosphopantetheine could constitute a directed overflow mechanism to prevent its oxidation to the S-sulfonate, sulfonate, or other forms. Hydrolyzing 4'-phosphopantetheine sulfonate or S-sulfonate would forestall their conversion to inactive forms of CoA and acyl carrier protein. May play a role in the physiological regulation of CoA intracellular levels (Probable).
Synonyms: FLJ10782; CTRCT49
Tractability: PROTAC: ubiquitination databases record sites on it; its protein half-life has been measured.
Gene: Protein-coding gene on chromosome 1 (2,508,534 to 2,526,612, reverse strand). Ensembl gene ENSG00000157881.
Subcellular location: Cytoplasm
Subcellular location (Human Protein Atlas): Cytosol
Pathways (Reactome):
Metabolism: Vitamin B5 (pantothenate) metabolism
Gene Ontology:
Molecular function: pantothenate kinase activity; phosphatase activity; ATP binding
Biological process: pantothenate metabolic process; coenzyme A biosynthetic process
Cellular component: cytoplasm; cytosol; nucleus
Genetic constraint (gnomAD): Loss-of-function variants: 33 observed, 66.86 expected, observed/expected ratio (o/e) 0.49, 90% interval 0.37 to 0.66. The upper end of that interval is the gene's LOEUF score, 0.66, which puts it in group 2 of 6, group 1 being the genes least tolerant of losing a copy. Missense variants: 844 observed, 963.19 expected, observed/expected ratio (o/e) 0.88, 90% interval 0.83 to 0.93. Synonymous variants: 489 observed, 426.22 expected, observed/expected ratio (o/e) 1.15, 90% interval 1.07 to 1.24.
Homologues: Orthologues: chimpanzee PANK4 (99% identical), macaque PANK4 (99% identical), pig PANK4 (95% identical), dog PANK4 (94% identical), guinea pig PANK4 (93% identical), rat Pank4 (92% identical), mouse Pank4 (92% identical), tropical clawed frog pank4 (82% identical), zebrafish pank4 (54% identical), Drosophila melanogaster CG5828 (21% identical), Caenorhabditis elegans pnk-1 (20% identical). Paralogues in human: PANK2 (18% identical), PANK1 (17% identical), PANK3 (17% identical).
Diseases named in the same sentence as PANK4 in open-access papers:
PANK4 is named in the same sentence as 20 diseases in open-access papers, as found by Europe PMC text mining. Sharing a sentence is not in itself a finding about the gene and the disease. The quoted sentences say what the papers report.
type 2 diabetes (2 papers, 2013 to 2023). "Studies in Han Chinese have shown that gene polymorphisms in PANK4 are associated with type 2 diabetes, and functional experiments have shown that PANK4 can affect the apoptosis of pancreatic β cells." (PMID 37196116, 2023). "PANK4 is located on chromosome 1p36.32 and was first described as a putative causative gene in type 2 diabetes in the Chinese population." (PMID 37196116, 2023).
acute myeloid leukemia (1 paper, 2024). Acute myeloid leukemia (AML) is a group of neoplasms arising from precursor cells committed to the myeloid cell-line differentiation. "Nevertheless, in line with previous studies on acute myeloid leukemia (AML), Kaplan–Meier survival analysis revealed that increased PANK4 mRNA expression is associated with decreased overall survival (OS) of patients suffering from GBM." (PMID 38353396, 2024).
autosomal dominant congenital cataracts (1 paper, 2021). "PANK4 has been linked to autosomal dominant congenital cataracts and BHLHE40 is a transcriptional repressor also involved in NOTCH signaling." (PMID 34215186, 2021).
cataract (1 paper, 2023). Partial or complete opacity of the crystalline lens of one or both eyes that decreases visual acuity and eventually results in blindness. "The PANK4 level was correlated with aging in cataract patients and mice." (PMID 37196116, 2023).
cognitive decline (1 paper, 2026). "Astrocyte-specific PANK4 ablation mitigates these effects, highlighting PANK4 as a potential therapeutic target for preventing or treating age-associated cognitive decline." (PMID 42212001, 2026).
colitis (1 paper, 2025). Inflammation of the colon. "The regulatory role of PANK4 in CD4+ T-cell proliferation was confirmed in models of experimental colitis and influenza A virus infection, where Pank4-deficient CD4+ T cells exhibited greater expansion than their wild-type counterparts when co-transferred." (PMID 40962808, 2025).
diabetes (1 paper, 2023). "Blood of diabetic patients was collected to examine the putative relationship between PANK4 and diabetes." (PMID 37196116, 2023).
fibrosis (1 paper, 2023). the formation of excess fibrous connective tissue in an organ or tissue in a reparative or reactive process. "By slit-lamp observation, an opaque anterior lens (fibrosis) was observed in the PKM-IN-1-treated group at 3 d, but a transparent lens was observed in the Veh group, which revealed PANK4 deficiency-dependent activation of PKM2." (PMID 37196116, 2023).
Glucose intolerance (1 paper, 2025). Glucose intolerance (GI) can be defined as dysglycemia that comprises both prediabetes and diabetes. "Deleting PanK4 impairs fatty acid oxidation and glucose uptake, leading to glucose intolerance, while increasing PanK4 enhances glucose metabolism, highlighting its potential in promoting metabolic health." (PMID 39746949, 2025).
influenza (1 paper, 2013). An acute viral infection of the respiratory tract, occurring in isolated cases, in epidemics, or in pandemics; it is caused by serologically different strains of viruses (influenzaviruses) designated A, B, and C, has a 3-day incubation period, and usually lasts for 3 to 10 days. "The majority of the hits were novel; however, PANK4, NEK8, ITPKB, CALM2 and HK2 have been identified in other influenza screens." (PMID 23805279, 2013). "In addition, four of the six (HK2, NEK8, PANK4, PLK4) have also been identified important for influenza virus replication in other influenza-genome screens." (PMID 23805279, 2013).
kidney cancer (1 paper, 2025). Primary or metastatic malignant neoplasm involving the kidney. "Consistent with our fly data, MYC binds to promoter regions of all four PANK genes in mammals, and its expression inversely correlates with that of PANK4 in human kidney cancer pRCC." (PMID 40832336, 2025).
virus infection (1 paper, 2025). "We further hypothesized that the increased proliferation of Pank4-deficient CD4+ T cells could play an improved protective role in a mouse model of virus infection." (PMID 40962808, 2025). "Specifically, during viral infections, targeting PANK4 may enhance T-cell responses." (PMID 40962808, 2025).
cancer (4 papers, 2022 to 2025). A tumor composed of atypical neoplastic, often pleomorphic cells that invade other tissues. "Future studies could assess the therapeutic potential of inhibiting PANK4 phosphatase activity to increase CoA synthesis in patients with pantothenate-kinase-associated neurodegeneration or selectively inhibiting CoA synthesis in PI3K-dependent cancers." (PMID 35896750, 2022). "Taken together, based on its highest z‐score rank and considering its largely unexplored, yet intriguing role in cancer, we focused on PANK4 in order to investigate its potential role as chemosensitizer of TMZ in GBM." (PMID 38353396, 2024). "Recently, Thr406 was identified as a insulin-responsive site on PanK4 in cultured cancer cells." (PMID 39746949, 2025). "As cancer cells depend on several compensatory mechanisms, especially following potential accumulation of lethal damage, the increase in PANK4 levels after TMZ treatment could provide an advantage to GBM cells." (PMID 38353396, 2024). "We found that several intermediate metabolites of the CoA synthesis pathway (e.g., 4’-Phosphopantetheine and 3’-Dephospho-CoA) were increased in PanK4 mKO muscles, supporting recent findings in cancer cells that PanK4 might act as a potential repressor of the CoA pathway." (PMID 39746949, 2025).
tumor (4 papers, 2022 to 2024). "Overall, PANK4 regulates tumor growth through the synthesis of CoA, providing a new idea for PI3K to treat tumors." (PMID 36329370, 2022). "A one-hour PI3K inhibitor treatment of non-tumour-bearing mice also decreased PANK4 phosphorylation in skeletal muscle, the tissue with the highest reported expression of PANK426." (PMID 35896750, 2022). "A ten-day PI3K inhibitor treatment of mice diminished PANK4 phosphorylation in Pik3cap.H1047R-expressing mammary allograft tumours that exhibit PI3K-dependent growth." (PMID 35896750, 2022). "While treatment of mice with sublethal doses of TMZ did not significantly affect tumor growth, susceptibility to the drug was significantly improved following PANK4 silencing, as shown by the pronounced reduction in tumor growth." (PMID 38353396, 2024). "Moreover, IHC analysis of cleaved caspase 3 in tumor tissues following PANK4 knockdown and TMZ treatment further confirmed a pronounced upregulation of cleaved caspase 3 compared to control samples treated with TMZ alone." (PMID 38353396, 2024). "The researchers discovered that tumors from Pik3cap.H1047R tumor-bearing mice treated with a PI3K inhibitor exhibited PANK4 phosphorylation and tumor growth in a PI3K-dependent manner; similar effects were observed in the skeletal muscle of non-tumor-bearing mice and in IGF-1–stimulated cells." (PMID 36329370, 2022). "More specifically, we showed that combined abrogation of PANK4 and TMZ treatment leads to attenuation of cell proliferation and clonogenicity, increased cell death in TMZ‐resistant GBM models, as well as decreased tumor growth in vivo." (PMID 38353396, 2024).
infection (2 papers, 2013 to 2025). The state of being infected such as from the introduction of a foreign agent such as serum, vaccine, antigenic substance or organism. "The results revealed greater numbers of Pank4-deficient (CD45.1-CD45.2+) CD4+ T cells in both the lungs and mediastinal lymph nodes 5 days post infection than did wild-type (CD45.1+CD45.2+) CD4+ T cells." (PMID 40962808, 2025). "Of the 17 HPK genes identified important for A/WSN/33 replication, six (CDK13, HK2, NEK8, PANK4, PLK4, SGK3) emulated the phenotype following A/New Caledonia/20/99 infection, i.e. increased or decreased virus replication as measured by influenza NP localization and influenza M gene levels." (PMID 23805279, 2013).
PANK4 also shares sentences with these, for which no sentence is quoted: Cognitive impairment (1 paper); Intellectual disability (1); lymphopenia (1); metabolic syndrome (1); neuroblastoma (1).